LINC00310 (long independently transcribed non-coding RNA 310)
Synonyms: C21orf82; NCRNA00310
Gene: Long non-coding RNA gene on chromosome 21 (34,157,724 to 34,325,034, forward strand). Ensembl gene ENSG00000227456.
Diseases named in the same sentence as LINC00310 in open-access papers:
LINC00310 is named in the same sentence as 5 diseases in open-access papers, as found by Europe PMC text mining. Sharing a sentence is not in itself a finding about the gene and the disease. The quoted sentences say what the papers report.
breast carcinoma (2 papers, 2018 to 2024). "In this study, LINC00310 was identified to be associated with prognosis of patients with breast cancer by interrogating the breast invasive carcinoma data set of the Cancer Genome Atlas (TCGA) at cBioPortal." (PMID 29993199, 2018). "The results showed that LINC00310 was increased as breast cancer progressed, and the deregulation of LINC00310 was significantly associated with patients’ survival." (PMID 29993199, 2018). "Linc00310 shows increased expression in coronary artery disease, and increased expression of Linc00310 is a marker for breast cancer." (PMID 39605035, 2024). "There was an obvious visual difference in the tumour size between the two groups (right), suggesting the role of LINC00310 in primary tumour growth of breast cancer." (PMID 29993199, 2018). "The results showed that serum LINC00310 expression in patients with breast cancer was significantly up‐regulated in comparison with healthy controls." (PMID 29993199, 2018). "To better characterize the oncogenic role of LINC00310, we further checked its expression in different cell lines and found that LINC00310 was up‐regulated in breast cancer cell line LM‐4142 compared with the non‐malignant HMLE cells." (PMID 29993199, 2018). "We then characterized LINC00310 by knockout (KO) cell models and revealed that LINC00310 played an oncogenic role in breast cancer both in vitro and in vivo." (PMID 29993199, 2018). "We determined the expression of LINC00310 by qRT‐PCR, using 95 serum samples, including 48 patients with breast cancer and 47 healthy controls." (PMID 29993199, 2018). "For example, LINC00310 was up‐regulated in breast cancer specimens." (PMID 29993199, 2018). "Given that LINC00310 might play an oncogenic role in breast cancer, we tried to evaluate whether LINC00310 could be used as a potential biomarker for diagnosis of breast cancer." (PMID 29993199, 2018). "Taken together, these findings suggest that LINC00310 may play an oncogenic role and can be explored as a prognostic biomarker for breast cancer." (PMID 29993199, 2018). "As deep sequencing becomes a commonly used tool to provide more valuable information, the expression data (RNA‐Seq) of LINC00310 were searched in breast cancer based on the Onco Query Language criteria “EXP ≥ 2” from the Cancer Genome Atlas (TCGA) data set at the cBioPortal for Cancer Genomics." (PMID 29993199, 2018). "In addition, we profiled breast cancer cDNA arrays from OriGene by qRT‐PCR, and the results showed that the LINC00310 expression was elevated in breast cancer tissues compared with the normal tissues." (PMID 29993199, 2018). "In summary, our results suggested that LINC00310, as an oncogene, could be considered as a potential candidate for prognostic evaluation of breast cancer, and it might promote tumorigenesis by regulating c‐Myc expression." (PMID 29993199, 2018). "The expression of LINC00310 was significantly higher in patients with advanced breast cancer compared with the patients with stage I breast cancer, indicating that it might be involved in the progression of breast cancer." (PMID 29993199, 2018).
breast invasive carcinoma (1 paper, 2018). "Here, we focused on LINC00310 by interrogating the breast invasive carcinoma data set of the Cancer Genome Atlas (TCGA)." (PMID 29993199, 2018).
cardiovascular diseases (1 paper, 2022). "In this study, GO analysis showed that LINC00310 in the ceRNA network was associated with cardiovascular system development, sprouting angiogenesis, and circulatory system development, which suggested thatLINC00310 may be involved in cardiovascular diseases." (PMID 36138345, 2022).
tumour (1 paper, 2018). "In consistent with in vitro results, we found that LINC00310 KO inhibited tumour growth compared with the vector control." (PMID 29993199, 2018). "Tumours derived from LINC00310 KO exhibited lower c‐Myc expression at both the mRNA and protein levels than those derived from vector control, further indicating that LINC00310 played a critical role in tumour growth through regulation of c‐Myc." (PMID 29993199, 2018). "We found that LINC00310 expression was increased as tumours progressed." (PMID 29993199, 2018). "As expected, we found little expression of LINC00310 in LINC00310 KO tumours." (PMID 29993199, 2018). "Moreover, the LINC00310 KO also decreased tumour weight (left)." (PMID 29993199, 2018). "Moreover, LINC00310 KO mice exhibited much less tumour growth and overall tumour weight." (PMID 29993199, 2018).
LINC00310 also shares sentences with these, for which no sentence is quoted: coronary artery disease (1 paper).